TTF1 (transcription termination factor 1)
Diseases named in the same sentence as TTF1 in open-access papers (continued):
Sharing a sentence is not in itself a finding about the gene and the disease.
lung carcinoma (continued). "Recent studies were addressed to the prognostic value of TTF-1-expression in lung carcinoma." (PMID 25889870, 2015). "Therefore, in the present case, we were able to diagnose the gallbladder tumor as metastasis from the primary lung cancer by immunohistochemical staining for TTF-1 and CK7." (PMID 25889744, 2015). "Therefore, instead of a lung-specific marker, TTF-1 can be used to discriminate between metastases from a primary lung cancer and primary gallbladder cancer." (PMID 25889744, 2015). "TTF-1 amplified lung cancers, exhibit increased RNA and protein expression." (PMID 25594059, 2014). "The purpose of this study was to clarify whether TTF-1 expression status can be used to predict EGFR mutation status to guide clinical treatment and improve the prognosis of patients with advanced lung cancer." (PMID 24743427, 2014). "Other prominent examples include MITF in melanoma and NKX2-1 (TTF1) in lung cancer." (PMID 24040285, 2013). "Knockdown of TTF1 in lung cancer cell lines with amplification led to reduced cell proliferation, manifested by both decreased cell-cycle progression and increased apoptosis indicating that TTF1 is a lineage-specific oncogene in lung cancer." (PMID 22928112, 2012). "We therefore used the A549 to study the role of TTF-1 in lung cancer cells." (PMID 22940844, 2012). "In this analysis, we used organ-specific antibodies, including TTF-1 for lung cancer, WT-1 or PAX8 for gynecological cancers, mammaglobin or GCDFP-15 for breast cancer, PSA for prostate cancer, CDX2 for gastrointestinal cancers, and uroplakin for urothelial cancers." (PMID 22299055, 2012). "Evaluating the immunohistochemical cytokeratin profile of the lesion in terms of CK7 and CK20 was useful when distinguishing between pulmonary adenocarcinoma and metastatic pulmonary tumor was difficult, along with levels of the lung cancer marker TTF-1 and the breast cancer marker GCDFP-15." (PMID 21989021, 2011). "TTF-1 is highly sensitive and specific for diagnosis of primary lung cancer." (PMID 20796281, 2010). "The nuclear thyroid specific transcription factor TTF-1 is a homeodomain-containing protein belonging to the Nkx-2 class of homeobox genes, which is required for proper thyroid development and is used as a marker of thyroid and lung carcinoma." (PMID 18958156, 2008). "Since CK7 and TTF-1 are specific markers for primary lung cancer and CK20 and β-catenin for colorectal cancer, combined immunohistochemistry of these markers may be valuable in discriminating diagnosis." (PMID 16451736, 2006). "However, the role of TTF-1 in the pathogenesis and biology of lung cancer is uncertain." (PMID 39456114, 2024). "In pathological routine practice, anti-CK7 and CK20 immunohistochemistry may be requested for diagnostic guidance, especially for TTF-1 negative and p40 negative lung cancer." (PMID 35885495, 2022). "Even in entities not listed as distinct favorable subtypes in the ESMO classification, as is the case for CK7+ TTF1+ carcinomas in patients with mediastinal or hilar lymph nodes or pleural carcinosis, the treatment should be dictated by the most likely primary, in this case lung cancer." (PMID 31165045, 2019). "However, the role of TTF-1 in lung cancer pathogenesis and biology is uncertain." (PMID 31196060, 2019). "Likewise, a CK7+, TTF1- adenocarcinoma lung mass might represent a primary lung cancer or alternatively a CUP with pulmonary metastasis." (PMID 31165045, 2019). "Moreover, the metastatic index of lung also decreased significantly (p < 0.05), indicating TTF-1-promoter-operating miR-7 expression also could significantly inhibit the metastasis of lung cancer cells in vivo, which was consistent with our previous report." (PMID 28325285, 2017). "Likewise, TTF1, p63, NapsinA, K-ras, EGFR are associated with the oncogenesis of lung cancer." (PMID 28938549, 2017).
lung carcinoma (continued). "Thus, to further verify the effect of TTF-1-promoter-operating miR-7 expression on the growth of lung cancer cells, we analyzed the expression of phosphorylation of Akt and Erk in tumor tissue derived from the p-T-miR-7 injection group or the p-Cont injection group, respectively." (PMID 28325285, 2017). "Real-time PCR assay showed that the expression level of the miR-7 in p-T-miR-7 transfection group was unmistakably higher than that in the control group (p < 0.05), indicating TTF-1 promoter could effectively operate the expression of miR-7 in lung cancer cells." (PMID 28325285, 2017). "Importantly, we found that TTF-1-promoter-operating miR-7 expression could effectively inhibit the growth of lung cancer cells in vitro and in vivo." (PMID 28325285, 2017). "In addition to genes associated with smoking the AC1/AC2 classifier included several genes implicated in lung cancer tumorigenesis, such as KITID1MMP7MYCNXRN2, and CYP24A1, as well as type II pneumocyte marker genes such as NKX2-1 (TTF1/TITF1), LAMP3 (CD208), and surfactant proteins SFTPB and SFTPC." (PMID 22676229, 2012). "Thyroid transcription factor-1 (TTF-1) and cytokeratin 7 (CK7) are markers used to diagnose the histological subtype of lung cancer and to distinguish primary LUAD." (PMID 40275403, 2025). "At the molecular level, TTF-1 has been postulated to positively regulate VEGF expression and the major signalling receptor for VEGF as VEGFR2 lung cancer epithelial cells." (PMID 37775725, 2024). "Previous studies have established TTF-1 expression is a good prognostic indicator for both OS and PFS in patients with advanced lung cancer." (PMID 39456114, 2024). "We found spontaneous development of lesions resembling TTF-1/P63-positive non-small-cell lung cancer (NSCLC), a rare subtype of lung cancer." (PMID 37324952, 2023). "Intriguingly, Fbxo45 was specifically and strongly expressed in tumor cells of NSCLC according to the indirect immunofluorescence analysis in paraffin‐embedded human lung carcinoma, including LUAD with TTF1‐positive and LUSC with TTF1‐negative." (PMID 35838331, 2022). "For example, an IHC panel that includes thyroid transcription factor-1 (TTF-1), Napsin A, CK5/6, p40, CD56, synaptophysin (Syn), and chromogranin (CgA) will be useful in the differentiation of the histological type of lung cancers." (PMID 34975346, 2021). "To see whether H1299RASSF1A tumours are well‐differentiated, we measured levels of TTF‐1 (thyroid transcription factor 1) and Mucin 5B, characterized markers for terminal lung differentiation for which expression in tumours is correlated with better prognosis and survival in lung cancer patients." (PMID 31268606, 2019). "In total, 340 lung cancer biopsies were investigated for the expression of CK5, TTF1, p63 and surfactant." (PMID 30379223, 2018). "The obtained data showed that TTF-1, P63, CK7, CD56 and/or 34βE12 represent a useful panel of antibodies to identify lung carcinoma subtypes in small bronchoscopic biopsies." (PMID 29531543, 2017). "Importantly, overexpression of NDUFA4 could abrogate the effect of TTF-1-operating miR-7 expression on the growth and metastasis of lung cancer cells, accompanied by altered transduction of the Akt and Erk pathway, which was critical for the growth and metastatic potential of lung cancer cells." (PMID 28325285, 2017). "Prognosis of SCLC was related to TTF-1 expression independently after adjusting smoking, ECOG score, stage and SVCS due to lung cancer." (PMID 28855032, 2017). "This trend held true in the two mouse lung cancer cell systems - 389T2 transfected with a human TTF-1 transgene and 394T4-shTtf-1 knockdown cells rescued with a human TTF-1 transgene." (PMID 26912193, 2016). "Immunostaining with TTF-1, CDX2, CK7, and CK20 is helpful to distinguish primary gastrointestinal carcinoma from metastasis of lung carcinoma." (PMID 25947890, 2015).
lung carcinoma (continued). "About 73%–88% of primary lung cancers and 2.4% of primary breast cancers are found to be TTF-1 positive, thus it is not reliable alone in ruling out a primary from metastatic breast cancer." (PMID 40134856, 2025). "The markers of lung carcinoma, such as TTF1, CK7, p40, and p63, showed absent or only focal weak expression." (PMID 40909976, 2025). "Interestingly, a previous translational study demonstrated that TTF-1 positively regulates VEGF and the major signalling receptor for VEGF as VEGFR2 lung cancer epithelial cells." (PMID 36233825, 2022). "TTF‐1 regulates the maturation and development of thyroid and lung, and many studies have shown a relationship between TTF‐1 expression and the occurrence of lung cancer." (PMID 35808895, 2022). "In contrast, most tuft cell-like lung cancers were negative for the highly specific neuroendocrine markers, chromogranin A and synaptophysin, and TTF1, a marker of pulmonary adenocarcinoma and SCLC." (PMID 36402755, 2022). "Our work on this retrospective cohort demonstrates that anti-CK7/CK20 immunohistochemistry in biopsies in patients with suspected TTF-1 and p40 negative primary lung cancer is of little value." (PMID 35885495, 2022). "Extensive P63 expression with focal TTF‐1 in the same tumor cell population is not common in lung cancer and should take the diagnosis as NMC into consideration." (PMID 34409758, 2021). "Regarding the diagnosis, the histological and immunohistochemical similarities (TTF-1, Napsin A, and CK7 were positive) with lung cancer were comprehensively evaluated, and this tumor could be diagnosed as an MPTLC." (PMID 32468270, 2020). "ROR1 expression is independent of classical lung cancer molecular alterations and not correlated, in a Caucasian cohort, to TTF-1 expression." (PMID 33172431, 2020). "Within this region, the transcription factors NKX2-1 (thyroid transcription factor-1; also known as TTF1), NKX2-8 and PAX9 are candidate genes that cooperate to control lung cancer cell growth, although other genes in this region are also likely to facilitate the tumorigenesis process." (PMID 30258080, 2018). "SMARCA2 and SMARCA4 deficiency was noted in 10% of nonsmall cell lung cancer cases, 80% of SMARCA2/SMARCA4 deficient tumors was also TTF-1 negative, and recently SMARCA4 loss was found to be a predictor of response to platinum based chemotherapy." (PMID 31093468, 2018). "Therefore, diagnosis is largely reliant on immunohistochemical staining; utilization of positive TTF-1, CK7, and CK20 as markers for diagnosis of primary lung carcinoma is essential." (PMID 26925278, 2016). "In our case, the immunophynotype of CK7 positive, CK20 negative and TTF1 positive makes the primitive nature of the lung cancer almost certain." (PMID 27217885, 2016). "Conversely, the PEAC phenotype did not express the “lung cancer marker” TTF-1 but was instead characterized by the “intestinal marker” CDX2." (PMID 26677401, 2015). "Reverse transcriptase-polymerase chain reaction (RT-PCR) was used to identify the presence of mRNA for NKX2-1, also known as TTF-1, a marker of lung differentiation, and eleven receptor and cytoplasmic tyrosine and serine/threonine kinases, in the BACA and CLAC canine lung cancer lines." (PMID 26560147, 2015). "It is known that the expression of TTF-1 is helpful to distinguish primary lung cancer from other non-pulmonary malignancies." (PMID 25889870, 2015). "TTF-1 is an immunhistochemical marker, which can help to differentiate between primary lung carcinoma and non-pulmonary cancer." (PMID 25889870, 2015). "Moreover, another obviously very expensive and time-consuming study on lung cancer subtypes testing >1000 cases with 108 antibodies got similar results, showing a five protein signature that could also separate cases that were undefined after TTF1/p63 analysis." (PMID 25325012, 2014).
lung carcinoma (continued). "The expanded H1975 lung cancer cells as well as patient CTCs from sample C23 expressed TTF-1 while the cultured fibroblasts lacked expression suggesting tumor specific markers are preserved in our model." (PMID 25474037, 2014). "However, the immunohistochemical panels included Ck7, Ck20, TTF-1, and KI67, which had further confirmed the primary lung cancer." (PMID 23119202, 2012). "TTF-1 positivity is a good indicator (but not a proof) of a primary lung carcinoma, but up to 25% of the adenocarcinomas are negative and most metastatic thyroid carcinomas would be positive." (PMID 20806071, 2010). "In our patient, TTF-1 was positive and no thyroid lesions were present, thus establishing a final diagnosis of primary lung cancer." (PMID 20796281, 2010). "It has been reported that positive staining of TTF-1 was observed in 70%–90% of primary lung cancer cases, but not in lung metastasis of colorectal cancer cases." (PMID 16451736, 2006). "Immunohistochemical staining of the gastric tumor revealed adenocarcinoma that was positive for TTF-1 and caudal-related homeodomain protein 2 (CDX2) and negative for napsin A. In contrast, lung cancer tissue was weakly positive for TTF-1 and negative for napsin A and CDX2." (PMID 41635529, 2026). "The co-expression of TTF-1 and p40 in NSCLC may define a novel subtype of lung cancer." (PMID 39928773, 2025). "We were the first to establish the TAMs‐lung cancer cell spheroids (M2/LLC spheroids) by incubating the M2‐like macrophages with LLC cells, followed by the verification using antibodies against TTF1 (the marker for LLC cells) and CD206 (the marker for TAMs) by immunofluorescence staining." (PMID 35988145, 2022). "Second, patients who were TTF-1-positive tended to have longer PFS and OS than patients who were TTF-1-negative in either regimen with or without PEM, indicating that that TTF-1-negative lung cancer may be resistant to chemotherapy." (PMID 36614938, 2022). "Unfortunately, neither MICE nor HIIE was able to change the level of TTF-1 in lung cancer tissues." (PMID 35371324, 2022). "Furthermore, TTF-1 staining was positive on the CAM tumor derived for the HCC827 lung cancer cell line, showing that there were no technical issues explaining the absence of staining in the cohort’s samples." (PMID 36077622, 2022). "Yet, how TTF-1 may influence chemosensitivity of lung cancer cells and thus contribute to its prognostic power was not fully understood." (PMID 31142791, 2019). "How TTF-1 may impact cellular responses to cisplatin, a standard chemotherapy for lung cancer, was not well characterized." (PMID 31142791, 2019). "Consistent with the observations in human lung cancers, these mouse results show that epithelial hyperplasia can develop into SCC, AD or ASC, and the developmental direction of epithelial hyperplasia can be reflected by expression of these markers, such as p63 and CK5 for SCC and TTF1 for AD." (PMID 31089135, 2019). "Therefore, we recommend that routine small biopsies of lung cancer without classic morphology should be subjected to a minimum immunohistochemical panel (TTF1 and p63, p40 or CK5) to differentiate ADC from SQCC." (PMID 30379223, 2018). "TTF-1 expression (OR=0.665, 95%CI: 0.472-0.937), smoking index ≤400 (OR=1.72, 95%CI: 1.061-2.789) and ECOG=2 (OR=3.551, 95%CI: 2.133-5.914), extensive-stage (OR=2.487, 95%CI: 1.793-3.451) and SVCS due to lung cancer (OR=2.394, 95%CI: 1.49-3.846) were independent prognostic factors for SCLC patients." (PMID 28855032, 2017). "Further mechanistic characterizations reveal that a surge of GM-CSF in the CM of TTF-1+ lung cancer cells may be the culprit for the negative angiogenic phenotype of the CM of TTF-1+ lung cancer cells." (PMID 26912193, 2016). "In fact, lack of TTF-1 expression is a constant feature of poorly differentiated lung carcinomas." (PMID 25859543, 2015).
lung carcinoma (continued). "If NRF2 is indeed responsible for the clusters downregulation in colon and lung cancer, it would concur with NRF2's role being in protection against cell damage and promoting cell survival (i.e. by preventing BCL-2 inhibition) and by allowing TTf1 upregulation." (PMID 24029073, 2013). "Thus, the histological examination is the only way to identify metastatic tumors to the gastrointestinal tract, and immunostaining with TTF-1, CDX2, CK7 and CK20 is also helpful to distinguish primary gastrointestinal carcinoma from metastasis of lung carcinoma." (PMID 22741562, 2012). "Importantly, we further found that TTF-1-promoter-operating miR-7 expression could significantly not only inhibit the growth and metastasis of human lung cancer cells in vivo, but also induce the apoptosis of cancer cells in vivo." (PMID 28325285, 2017). "Interestingly, we found that the expression level of miR-7 was higher in lung cancer cells, including 95D cells, A549 cells, and NCI-H292 cells, than in other types of tumor cells (p < 0.05), indicating higher intrinsic activity of TTF-1 promoter in lung cancer cells." (PMID 28325285, 2017). "However, hypoxia did not further increase the secreted VEGF level of the TTF-1+ lung cancer cells." (PMID 26912193, 2016). "But we found that ectopically expressing miR-29c inhibitors without the treatment of TGF-β1 inhibited the mRNA expression of TTF-1 and E-cadherin, and enhanced the expression of vimentin and α-SMA, which indicated that the inhibition of miR-29c could be sufficient to induce EMT in lung cancer." (PMID 27829234, 2016). "In a study assessing the immunohistochemical expression of TTF-1 in 34 primary and 27 non-primary canine lung tumors, TTF-1 was 100% specific and 85% sensitive for primary lung carcinoma." (PMID 39902337, 2024). "The results of the lung tumor showed positive for TTF-1, Napsin-A, and CK7, while negative for CDX2 and CK20, ruling out the possibility of gastrointestinal origin and indicating primary lung cancer." (PMID 39465837, 2024). "Immunohistochemical analysis showed positive results for TTF-1, Napsin A, and CK7, but CK20 did not present significant staining, and these findings indicated this tumor to be lung cancer metastasis rather than IPMN." (PMID 32468270, 2020). "Therefore, the expression of TTF1 and p63 in NCI-H596 cells is not one or the other, which provides evidence for the transdifferentiation between lung cancer cells due to the drug treatment." (PMID 39735556, 2024). "In the immunochemistry analysis, we could not find any feature of tissue-specific differentiation, with no staining of TTF-1 and CKAE-1-AE3 on the CAM tumors derived from our lung cancer patients." (PMID 36077622, 2022). "It should be noted that TTF-1 staining is clone dependent and not entirely specific for the lung (or thyroid); TTF-1 may be positive in non-SCLCs and maybe positive in non-lung cancers, e.g., colorectal cancer, endometrial cancer, and lymphoma." (PMID 37139017, 2023). "Although TTF-1 is a transcription factor that is not directly druggable by small molecules, studies such as the present one may shed new light on exploiting TTF-1 to improve lung cancer management." (PMID 31142791, 2019).